PCDH10 (protocadherin 10)
Diseases named in the same sentence as PCDH10 in open-access papers (continued):
Sharing a sentence is not in itself a finding about the gene and the disease.
cancer (36 papers, 2010 to 2026). A tumor composed of atypical neoplastic, often pleomorphic cells that invade other tissues. "Epigenetic changes contribute to cancer progression by hypermethylation and silencing of target TSGs, and PCDH10 hypermethylation has been shown to cause PCDH10 downregulation in certain cancers." (PMID 37147733, 2023). "In cancer, PCDH10 has been linked to both these processes, but in the telencephalon, we could not observe an overall reduction of Gsh2-lineage interneurons at E17.5." (PMID 38889770, 2024). "Further research is required to fully elucidate the role of Pcdh10 in neurological conditions and different types of the cancers, and determine whether Pcdh10 is implicated in any other human condition." (PMID 37058252, 2023). "Additionally, Pcdh10 can serve as a non-invasive diagnostic and prognostic indicator for various cancers." (PMID 37058252, 2023). "However, although the involvement of PCDH10 has been extensively elucidated in several cancers, the specific mechanisms underlying its silencing via promoter hypermethylation in GC remain elusive." (PMID 37147733, 2023). "The further use of our mice with floxed Pcdh10 alleles might become a most rewarding tool in contemporary cancer research." (PMID 35468745, 2022). "Failure to express PCDH10 may result in loss of inhibition of cell migration, thereby contributing to cancer progression." (PMID 22245948, 2012). "Among the candidate genes, hypermethylation of PCDH10 was implicated in other cancers." (PMID 20051947, 2010). "Some reports showed that PCDHs are dysregulated in various cancers, such as PCDH10, PCDH17 and PCDH8." (PMID 39123216, 2024). "Accumulating evidence has shown that PCDH10 is a TSG in several cancers, and its ectopic expression can inhibit tumorigenesis, suppress cell metastasis, and induce apoptosis." (PMID 37147733, 2023). "In this review, we explore the role of Pcdh10 in neurological disease and human cancer, and provide further insight into the molecular mechanisms and disease-relationship that Pcdh10 controls." (PMID 37058252, 2023). "Though the involvement of Pcdh10 in the pathogenesis of neural diseases and human cancers has been recently established, our understanding of the molecular functions and related signaling pathways involved is limited." (PMID 37058252, 2023). "Although the Pcdh10 gene is widely expressed in normal tissues, it is silenced or decreased in malignant tumors." (PMID 37058252, 2023). "Protocadherin 10 (PCDH10) has been identified as a functional TSG that is frequently silenced by DNA methylation in various human primary cancers, and PCDH10 methylation is an adverse prognostic marker in several cancers." (PMID 37147733, 2023). "Protocadherin 10 (PCDH10) is a newly identified TSG in various cancers and is downregulated in GC; however, the specific mechanisms of PCDH10 in GC remain elusive." (PMID 37147733, 2023). "On the other hand, the breeding of these mice bearing floxed Pcdh10 alleles with suitable Cre-expressing mice and with available mouse cancer models will be a most valuable addition to the research on PCDH10 inhibition in cancer." (PMID 35468745, 2022). "This suggests that PCDH10 methylation can be used as a marker for early stage cancer diagnosis, and the counting of methylated CpG islands has clinical prognostic assessment applicability." (PMID 33369468, 2020). "As expected, PCDH10 methylation status correlated with the lack of expression of the corresponding transcript in PCDH10 fully methylated cancer cell lines and, conversely, with expression of PCDH10 in the unmethylated cell line analyzed." (PMID 31088413, 2019). "It was previously shown that expression levels of protocadherins, such as PCDH8, PCDH10, and PCDH20, were downregulated by promoter methylation in various carcinomas, which were strongly associated with advanced cancer or poor outcome." (PMID 27351130, 2016).
cancer (continued). "With both PCDH10 and RASSF1A, methylation was very rare in controls (2.97% and 5.45%, respectively), but exceedingly common in cancer cases (94.06% in PCDH10 and 83.17% in RASSF1A) with highly significant differences (p < 0.001) using the chi-square test." (PMID 27330867, 2016). "Using methylation-specific polymerase chain reaction assays, methylation of PCDH10 promoter was assessed in cancer tissues of 109 patients who underwent curative resection of pathological stage I NSCLC." (PMID 26276761, 2015). "Here we further identified and characterized the promoter and elements that regulate PCDH10 expression in human MM patient samples and cancer cells." (PMID 22245948, 2012). "Current literature shows that genetic and epigenetic deregulation of PCDH10 occurs in a multitude of human cancers." (PMID 22245948, 2012). "An increasing number of studies have demonstrated that Pcdh10 plays an important role in cancer." (PMID 37058252, 2023). "Notably, hsa_circ_0001666 can also suppress Wnt/β‐catenin signaling, a well‐known cancer‐promoting pathway, via promoting PCDH10 expression." (PMID 37058252, 2023). "In general, these results highlight the potentiality of targeting Pcdh10 gene in human cancers." (PMID 37058252, 2023). "Regarding ectopic re-expression of human PCDH10, such experiments have been reported for a multitude of different human cancer cell lines, but as far as we could find out, this was done exclusively for the long isoform of PCDH10." (PMID 35468745, 2022). "In summary, inactivation of PCDH10 is widespread in a large variety of human cancers." (PMID 35468745, 2022). "Several studies indicated that PCDH10 could inhibit the canonical Wnt/β‐catenin signalling pathway, a well‐known cancer‐promoting pathway." (PMID 34841662, 2021). "Promoter methylation of PCDH10 was observed in cancer cells, and the expression of PCDH10 could be restored by 5-aza-2′-deoxycytidine." (PMID 32701143, 2020). "The expression of PCDH10 also showed a significant increase when compared to the control (P<0.001).Fluorescence microscope indicated morphological changes due to apoptosis in U87MG cancer cells, after treatmentwith cytochalasin H (10-5M, 48 hours)." (PMID 30507090, 2019). "Furthermore, the prognostic prediction of PCDH10 methylation revealed in many carcinomas was also investigated in our RCHOP-treated cohort." (PMID 29202805, 2017). "Similar to CDH1, PCDH10 inhibits cancer cell motility and migration." (PMID 26871474, 2016). "PCDH10 silencing in cancer cell lines was well correlated with its promoter CpG methylation, which could be restored by pharmacological demethylation, suggesting that promoter methylation of PCDH10 plays an important role in its inactivation in MM." (PMID 22245948, 2012). "Protocadherin 10 (1040 amino acids; 112,936 Da) and Protocadherin 17 (1159 amino acids; 126,229 Da) may play roles in specific cell–cell connections in the brain; protocadherin 10 seems to be involved in inhibiting cancer cell motility and cell migration." (PMID 37509254, 2023). "We also found five genes discovered by the consensus DEA and PCA and annotated as candidate cancer genes in NCG: AJAP1, CD1B, CDH2, PABPC4L, and PCDH10." (PMID 40788820, 2025). "Restoration of PCDH10 expression significantly suppressed tumorigenesis both in vitro and in vivo, by inhibiting epithelial-mesenchymal transition (EMT) and cancer stemness." (PMID 41608634, 2026).
cancer (continued). "CYP24, FOSB, PCDH10, THBS2, and RASSF5 were selected as representative genes for further analysis, as they are well-known regulators of cancer cell proliferation and apoptosis, and the results obtained by qPCR analysis were shown to support our previously obtained results." (PMID 29156803, 2017). "Protocadherin 10 (PCDH10) belongs to the non-clustered protocadherin and is reported to be widely expressed but frequently silenced by promoter methylation in many carcinomas and hematological malignancies." (PMID 26276761, 2015). "Animal cancer models with Pcdh10 inactivation have not been reported." (PMID 35468745, 2022). "Notably, the methylation status of PCDHAC2 and PCDHGC5 were never analyzed before in PDAC, while PCDH10 had been previously studied in PDAC cancer cell lines and one study analyzed this gene in PDAC primary tumors." (PMID 31088413, 2019).
infection (4 papers, 2022 to 2025). The state of being infected such as from the introduction of a foreign agent such as serum, vaccine, antigenic substance or organism. "Clonal PCDH10-knockout HEK 293T cells became resistant to infection by WEEV 71V RVPs encoding GFP, and infection could be rescued by PCDH10 overexpression." (PMID 39048821, 2024). "Treatment with HsPCDH10EC1-Fc blocked infection by all mutants with restored mammalian PCDH10 recognition (Mut-1, Mut-3, and Mut-5)." (PMID 40187345, 2025). "PCDHGA6 was upregulated in mice infected with Plasmodium berghei, and a gene that activates PCDHGA6 and PCDH10 was downregulated in experimentally infected 'amakihi that succumbed to infection." (PMID 40909016, 2025). "WEEV 71V RVPs robustly infected wild-type neurons, but infection was almost completely abolished in Pcdh10−/− neurons." (PMID 39048821, 2024). "Additional studies will be required to clarify the relative roles of WEEV binding to PCDH10 or MXRA8 in infection of avian hosts." (PMID 39048821, 2024). "PCDH10 supports WEEV E2–E1 glycoprotein-mediated infection of primary mouse cortical neurons, and administration of a soluble form of PCDH10 protects mice from lethal WEEV challenge." (PMID 39048821, 2024). "Conversely, RAP treatment did not inhibit McMillan RVP infection of wild-type neurons, indicating that access to PCDH10 as a receptor was sufficient for infection." (PMID 39048821, 2024). "Our finding that VLDLRLBD–Fc could block WEEV McMillan RVP infection of K562 cells stably expressing PCDH10 suggests that group A strains recognize PCDH10 and VLDLR through an overlapping surface on their E2–E1 spike proteins." (PMID 39048821, 2024). "Indeed, K562 cells transduced to express sparrow PCDH10 were rendered permissive to infection with Imperial 181 RVP strain." (PMID 39048821, 2024). "PCDH10 overexpression resulted in robust WEEV 71V RVP infection of these cells." (PMID 39048821, 2024). "Furthermore, there were nine proteins that were specifically detected at 7 days post-infection (Saa2, Trappc1, Cxadr, Armc8, Hbxip; Lamtor5, Prppsap2, Usp46, Pcdh10, Neo1)." (PMID 36061859, 2022). "For instance, among the genes upregulated in infected wild‐caught birds reported here, RAB20 was also upregulated in 'amakihi surviving experimental infection, and three upregulated genes (COG5, BOD1, and PCDH10 which activates PCDHGA6) were downregulated in 'amakihi that perished." (PMID 40909016, 2025). "To confirm that PCDH10, VLDLR and ApoER2 can support infection by group A WEEV strains, we rescued replication-competent WEEV Fleming and McMillan from molecular clones, and found they replicated faster and to higher levels in K562 cells expressing PCDH10, VLDLR or ApoER2 than in control cells." (PMID 39048821, 2024). "A PCDH10 construct in which EC1 is deleted could not support WEEV 71V RVP infection when ectopically expressed on K562 cells, suggesting that WEEV binds PCDH10 EC1." (PMID 39048821, 2024). "Infection by WEEV 71V RVPs of HEK 293T cells, SK-N-SH (a human neuroblast cell line) and SVG-A (a human astrocyte cell line) could also be blocked by polyclonal antibodies against PCDH10, but not by an isotype control antibody." (PMID 39048821, 2024).
neurodevelopmental disorder (3 papers, 2014 to 2020). A behavioral and cognitive disorder with onset during the developmental period that involves impaired or aberrant development of intellectual, motor, or social functions. "Interestingly, they also report hypoactivity in the active phase in three other mouse models of neurodevelopmental disorders: Cntnap2−/−, Pcdh10+/−, and Fmr1 KO mice." (PMID 33396736, 2020).
PCDH10 also shares sentences with these, for which no sentence is quoted: bladder cancer (4 papers); endometrial endometrioid carcinoma (2); gastric tumors (2); leukemia (2); B-cell lymphoma (1); bipolar disorder (1); chronic gastritis (1); chronic pancreatitis (1); chronic tonsillitis (1); colon cancer (1); colorectal (1); colorectal tumors (1); embryonal carcinoma (1); esophageal cancer (1); fragile X syndrome (1); gastrointestinal stromal tumor (1); gastrointestinal tumors (1); Gestational Diabetes Mellitus (1); hematological malignancies (1); Hypertension (1); malaria (1); microcephaly (1); neurological disorders (1); non-Hodgkin lymphoma (1); psychiatric disorder (1); seminoma (1); T-cell lymphoma (1); yolk-sac tumour (1).